SIRT1 (sirtuin 1)
Diseases named in the same sentence as SIRT1 in open-access papers (continued):
Sharing a sentence is not in itself a finding about the gene and the disease.
endometriosis (continued). "Three years later, the same study group inspected the role of Sirtuin 1 in endometriosis and observed significant overexpression in both epithelial and stromal cells of patients with endometriosis." (PMID 37174627, 2023). "SIRT1 overexpression in endometriotic lesions worsens endometriosis development, but the application of Sirt1 inhibitor EX527 shows improvement." (PMID 37600694, 2023). "Early evidence has demonstrated that SIRT1 inactivation protects mice against implantation failure, decidualization defects, and progesterone resistance, suppressing the progression of endometriosis." (PMID 37353804, 2023). "SIRT1 participates in the endometrial microenvironment for decidualization and exhibits unique expression patterns in endometriosis." (PMID 37353804, 2023). "SIRT1 function is closely related to female reproductive diseases, such as endometriosis, polycystic ovary syndrome, and aging-related infertility, by mediating caloric homeostasis, improving mitochondrial function, and affecting chromatin recombination." (PMID 37060101, 2023). "BCL6 was chosen based on its previously reported elevated expression in endometrial biopsies, and SIRT1 is co-expressed and upregulated in the endometrium of women with endometriosis." (PMID 34698105, 2021). "Resveratrol, a polyphenol and a potentially effective therapeutics option for endometriosis, was found as a SIRT1 activator through upregulating NMNAT1 to increase NAD+." (PMID 34721014, 2021). "The average serum concentration of SIRT1 in patients with stages I and II (combined) of endometriosis was 932.3 pg/mL with a sample size of ten." (PMID 34698105, 2021). "Based on the results of this exploratory study, the feasibility of using BCL6 and SIRT1 as protein markers in bodily fluids (such as serum, cervical swab, and urine) for a non-invasive diagnosis of endometriosis is relatively low." (PMID 34698105, 2021). "The future utility of SIRT1 as a marker for endometriosis needs to be tested further with increased sample sizes for both negative controls and women with endometriosis of various stages." (PMID 34698105, 2021). "A recent study demonstrated a KRAS activation-triggered SIRT1 overexpression in women with endometriosis, which has been suggested to contribute to infertility and the pathogenesis of endometriosis." (PMID 34744791, 2021). "Comparing SIRT1 values between patients with stages I and II of endometriosis with the control patient group resulted in a p-value of 0.4213." (PMID 34698105, 2021). "The potential of SIRT1 marker for advanced asymptomatic endometriosis needs to be investigated further with larger patient sample size." (PMID 34698105, 2021). "Targeting SIRT1 with small molecule inhibitors thus serves as a potential therapeutic treatment for endometriosis-mediated IVF failure." (PMID 34744791, 2021). "Nevertheless, SIRT1 suppressed inflammatory cytokines in endometriosis, and activated NF-kB deacetylation to induce apoptosis in tumors." (PMID 34721014, 2021). "While there was an initial decrease in SIRT1 levels noted for women with endometriosis stages I/II, the expected upregulation of SIRT1 was found to have occurred with increased disease severity in stages III/IV." (PMID 34698105, 2021). "SIRT1 has been found to be overexpressed in the endometrium of women with endometriosis and co-expressed with BCL6." (PMID 34698105, 2021).
endometriosis (continued). "This project aims to determine if differential expression of B-Cell Lymphoma 6 (BCL6) and Sirtuin 1 (SIRT1) proteins can be used as a marker to aide in the diagnosis of endometriosis through less invasive means." (PMID 34698105, 2021). "Considering similarity of endometriosis with solid tumors, it seems that the expression of SIRT1 changes in EEE compared to NE." (PMID 31531066, 2019). "Resveratrol has been reported as a potent antiinflammatory compound activating AMPK-SIRT1 pathway and it has been suggested to supress TNF-α-induced IL-8 release from the endometrial stromal cells via SIRT1 pathway in endometriosis." (PMID 29958542, 2018). "We believe SIRT1/BCL6 represent a more proximal defect in endometrium of women with endometriosis that interferes with early signaling of P4." (PMID 28754906, 2017). "To better understand the finding of increased KRAS in the endometrium of women with endometriosis, we investigated the association between KRAS activation and SIRT1 expression." (PMID 28754906, 2017). "In the present study, we report that BCL6 and SIRT1 are over-expressed and co-localize in the nuclei of endometrial cells from women with endometriosis." (PMID 28754906, 2017). "The levels of SIRT1 protein were significantly increased in the samples from women with endometriosis (n = 54) compared with controls (n = 11)." (PMID 28754906, 2017). "In this study, we investigated the levels of KRAS and SIRT1 proteins in eutopic endometrium from women with endometriosis." (PMID 28754906, 2017). "SIRT1 is highly expressed in the endometrium of patients with endometriosis and appears to be an excellent biomarker in endometrium of women with this disorder." (PMID 28754906, 2017). "In this study, we demonstrated for the first time that SIRT1 is over-expressed in women with endometriosis compared to controls by western blot and immunohistochemistry, correlating directly with elevated BCL6 expression." (PMID 28754906, 2017). "Significantly higher levels of SIRT1 in both eutopic ESCs and EECs of endometriosis patients." (PMID 40072055, 2025). "Many studies have related sirtuins with endometriosis, particularly Sirtuin 1 (SIRT1), which it has been suggested that may serve as potential biomarkers for endometriosis or for example, in animal models it has been described as part of the pathogenesis." (PMID 41009667, 2025). "Furthermore, NNMT-stabilized SIRT1 plays a role in decidualization defects, progesterone resistance and progression of endometriosis." (PMID 39489776, 2024). "One the limitations in endometrosis is This observation supports that genetic and epigenetic incident favors endometrial epithelia cells escape from senescence and fuel EMT process in endometriosis, what could be overcome by downregulation of SIRT1." (PMID 35853978, 2022). "Once transcribed, BCL6, with the help of SIRT1, could inactivate regulators of progesterone but also lead to implantation defects and repeated miscarriages in patients with endometriosis." (PMID 36294483, 2022). "Therefore, endometrial epithelial cells retain the potential to escape senescence by mechanisms that involve ectopic SIRT1 overexpression in endometriosis." (PMID 35853978, 2022). "The expression of SIRT1 was investigated in endometriosis and control tissues by IHC." (PMID 35853978, 2022). "Furthermore, BCL6 and SIRT1 are over-expressed in the eutopic endometria of women with endometriosis." (PMID 34698105, 2021). "At present, there are many related studies on the role of EZH2 and SIRT1 in endometriosis." (PMID 34790699, 2021). "Some studies have suggested that SIRT1 may promote endometrial tumor growth, and others described its potential role in endometriosis and embryo endometrial receptivity." (PMID 33435147, 2021).
endometriosis (continued). "Additionally, they reported coordinated activation of KRAS (Kirsten rat sarcoma virus) and over-expression of SIRT1, a histone deacetylase and gene silencer, in the eutopic endometrium from women with endometriosis throughout the menstrual cycle." (PMID 33435147, 2021). "SIRT1 is a main stimulator of cell growth and angiogenesis, two main events in endometriosis." (PMID 31531066, 2019). "To determine whether SIRT1 physically interacts with BCL6, we performed immunoprecipitation with SIRT1 antibody in total protein lysates from Ishikawa human endometrial adenocarcinoma cell line and endometrium from endometriosis patients." (PMID 28754906, 2017). "To determine that SIRT1 and BCL6 proteins are overexpressed as part of endometriosis development, we performed immunohistochemical analysis of SIRT1 and BCL6 in eutopic baboon endometrium sequentially after the experimental induction of the disease (n = 4 per time point)." (PMID 28754906, 2017). "The goal of our study was to determine if levels of SIRT1 and/or BCL6 were differentially expressed in any of these bodily fluids and could potentially be used as part of a less invasive diagnostic test for the presence of endometriosis." (PMID 34698105, 2021). "This points towards the possible utility of serum SIRT1 levels as a predictor of advanced endometriosis that may not be associated with severe symptoms or pain, rather than an initial screening for the disease itself." (PMID 34698105, 2021). "Besides, Sirt1, a mammalian homolog of silent information regulator 2 (Sir2), may be involved in endometriosis pathogenesis." (PMID 33325132, 2021). "Both SIRT1 and BCL6 bind to the GLI1 promoter and suppress its expression, leading to a reduction in GLI in women with endometriosis." (PMID 37108154, 2023). "Another previous study demonstrated that Sirtuin 1 (SIRT1) and BCL6 overexpressed and suppressed the promoter of GLI1, contributing to progesterone resistance and the pathogenesis of endometriosis." (PMID 36865552, 2023). "HDAC1, HDAC2, HDAC3, Sirtuin 1, and Sirtuin 3, are the five most studied HDAC enzymes which seem to, at least partly, influence the pathophysiology of endometriosis." (PMID 37174627, 2023). "Although previous literature demonstrated that EMT and endometriosis are closely associated with SIRT1 genes, indicating the involvement of SIRT1 in the pathogenesis of endometriosis, no study has been performed to explore whether SIRT1 regulates EMT and senescence in endometriosis." (PMID 35853978, 2022). "In sum, the effects of gamma-oryzanol as a therapeutic agent to alleviate pathogenesis of endometriosis in rats were investigated by the protein level of ER-α, SF1, SIRT1, HO-1, LC3 and BECN1." (PMID 35181729, 2022). "The average serum concentration of SIRT1 in patients with stages III and IV of endometriosis was 2357.5 pg/mL with a sample size of ten." (PMID 34698105, 2021). "The elevation of SIRT1 serum levels in stages III/IV follows the prediction by earlier studies of endometriosis which anticipated a rise in markers of inflammatory cascade such as BCL6 and SIRT1." (PMID 34698105, 2021). "When the average SIRT1 serum concentration in patients with stages I and II was compared to the average SIRT1 concentration from patients with stages III and IV endometriosis, a t-test resulted in a p-value of 0.0038, indicating a significant difference." (PMID 34698105, 2021). "Since both SIRT1 and BCL6 are differentially expressed in the eutopic endometrium of women with endometriosis, these two proteins were chosen for our study using ELISA assay of bodily fluids including serum, plasma, urine, saliva, and cervical swab." (PMID 34698105, 2021).
endometriosis (continued). "The authors suggest that KRAS, SIRT1, and BCL6 are coordinately over-expressed in the eutopic endometrium of women with endometriosis and likely participate in the pathogenesis of endometriosis." (PMID 33435147, 2021). "In turn, reduced expression of GLI1 was shown in the endometrium of women with endometriosis, confirming a mechanistic role for STAT3, BCL6, and SIRT1 overexpression in the P4 resistance of endometriosis." (PMID 31387263, 2019). "Together with SIRT1 and BCL6, KRAS was overexpressed in the eutopic endometrium of women with endometriosis." (PMID 29750165, 2018). "We report here for the first time in endometrium, direct protein-protein interactions between SIRT1 and BCL6 in human endometrial tissue, co-localizing in the nuclei of endometriosis cases." (PMID 28754906, 2017). "Perhaps most striking was the concurrent up-regulation of both proteins in baboon model of endometriosis, both BCL6 and SIRT1 appearing within 9 months of induction of the disease." (PMID 28754906, 2017). "The immunofluorescence results show that SIRT1 and BCL6 proteins were co-localized in endometrial epithelial cells of endometriosis patients." (PMID 28754906, 2017). "Since both proteins appear to be elevated, we analyzed the relationship between SIRT1 and BCL6 proteins in eutopic endometrium of endometriosis patients." (PMID 28754906, 2017). "Our results showed a strong positive correlation between SIRT1 and BCL6 levels in women with endometriosis throughout the menstrual cycle phases (n = 44)." (PMID 28754906, 2017). "Further, elevated levels of SIRT1 and BCL6 in secretory phase endometrium of women with endometriosis likely accounts for the decrease noted in GLI1 protein expression, as a sign of P4 resistance." (PMID 28754906, 2017). "Together, these data suggest that KRAS, SIRT1 and BCL6 are coordinately over-expressed in eutopic endometrium of women with endometriosis and likely participate in the pathogenesis of endometriosis." (PMID 28754906, 2017). "Here we report coordinated activation of KRAS and over-expression of Sirtuin 1 (SIRT1), a histone deacetylase and gene silencer, in the eutopic endometrium from women with endometriosis throughout the menstrual cycle." (PMID 28754906, 2017). "The levels of SIRT1 and BCL6 proteins were significantly increased at 9 and 15 months post-inoculation during endometriosis progression." (PMID 28754906, 2017). "EGCG has been shown to reduce oxidative stress and inflammation via the sirtuin 1 / nod-like receptor protein 3 (SIRT1/NLRP3) pathway, which may contribute to its protective effects against endometriosis." (PMID 41608512, 2026). "The upregulation of Sirtuin 1 (SIRT1), a nicotinamide adenine dinucleotide (NAD)-dependent protein deacetylase, promotes epithelial–mesenchymal transition by inducing senescence escape in murine endometriosis." (PMID 40643476, 2025). "Therefore, the present work assesses the effects of GO in rat models with surgically induced endometriosis, by evaluating the western blotting expression of ER-α, SF1, SIRT1, HO-1, LC3B, BECN1." (PMID 35181729, 2022). "The genes of ER-α, SF1, SIRT1, HO-1, LC3B, and BECN1 are involved in the endometriosis." (PMID 35181729, 2022). "The authors observed a correlation between SIRT1 and BCL6 expression in endometriosis." (PMID 33435147, 2021). "The average SIRT1 concentration in sera for patients without endometriosis was 1141.6 pg/mL with a sample size of ten." (PMID 34698105, 2021). "To determine the cell-specific expression of KRAS and SIRT1, we performed immunohistochemical analysis in endometrium from women with and without endometriosis." (PMID 28754906, 2017). "The levels of SIRT1 were also significantly higher in both the stromal and epithelial cells of endometriosis patients compared to women without endometriosis." (PMID 28754906, 2017). "Thus, both SIRT1 and BCL6 over-expression can be regulated through inflammatory cytokines known to be present in women with endometriosis." (PMID 28754906, 2017).
endometriosis (continued). "Finally, comparison of serum SIRT1 levels from patients with no endometriosis with serum from patients with stage III or stage IV endometriosis resulted in a p-value of 0.0152." (PMID 34698105, 2021). "In control women KRAS and SIRT1 proteins were weakly detected in the stromal and epithelial cells of endometrium from the proliferative phase and early, mid, and late secretory phases in women without endometriosis (n ≥ 4 per phase)." (PMID 28754906, 2017). "Furthermore, the identification of upregulated genes, such as SIRT1, SBDS, SRF, SPN, P2RX1, TEAD3, and SLITRK3, alongside downregulated genes, including KIF22, KIF25, GAS2L2, and HINT3, highlights a broad transcriptional reprogramming within endometriosis-affected tissues." (PMID 41516028, 2025). "However, if the endometrial overexpression of BCL6 and SIRT1 in patients with endometriosis could be extended to levels of BCL6 and SIRT1 in their serum or plasma, the diagnosis of the disease could be made significantly less invasive and more accessible to patients." (PMID 34698105, 2021). "However, the role of SIRT1 in endometriosis and uterine biology has not been examined." (PMID 28754906, 2017). "Furthermore, sirtuin 1 (SIRT1), a transcriptional regulator associated with both oncogenic and tumor-suppressor roles, binds and co-localizes with BCL6 and is also up-regulated in endometrium from women and non-human primates with endometriosis, significantly correlating with BCL6 expression levels." (PMID 31387263, 2019). "The levels of SIRT1 and KRAS were compared in endometrium of women with and without endometriosis." (PMID 28754906, 2017). "In addition, sirtuin 1 (SIRT1), a histone deacetylase and gene silencer, co-localizes with BCL6 in the nuclei and is upregulated in the endometrium of women and non-human primates with endometriosis." (PMID 37108154, 2023).